DMD (dystrophin)
Diseases named in the same sentence as DMD in open-access papers (continued):
Sharing a sentence is not in itself a finding about the gene and the disease.
epilepsy (11 papers, 2016 to 2025). A brain disorder characterized by episodes of abnormally increased neuronal discharge resulting in transient episodes of sensory or motor neurological dysfunction, or psychic dysfunction. "However, all DMD patients with epilepsy surveyed to date were found to have mutations outside the Dp116 coding region of the DMD gene, suggesting that Dp116 deficiency is unrelated to epilepsy." (PMID 28974057, 2017). "Serum GDF15 was elevated in 15 patients (upper limit 297.568 pg/ml), including 8 patients with epilepsy (8/15, 53%), 3 patients with myasthenia gravis (3/6, 50%), 3 patients with DMD (3/7, 42.9%), and 1 patient with viral encephalitis (1/2, 50%)." (PMID 35498801, 2022). "The overlaid disease annotations show strong co-expression between dystrophin isoforms and other diseases such as epilepsy, mental retardation, obesity, nervous system malformation, neurodevelopmental disorders and cardiovascular problems." (PMID 28974727, 2017). "This is the first study that reports on a (full-length) dystrophin upregulation in epilepsy, which justifies more research in order to further investigate this newly emerging relationship between hyperexcitation and dystrophin." (PMID 27458343, 2016). "Phenotypic variability could be explained by the co-expression networks between Dp427, Dp140, and Dp71 isoforms and genes involved in ID, NDDs, and epilepsy as dystrophin isoforms might interact with these genes’ protein products." (PMID 41595432, 2025). "Nineteen patients had serum FGF21 levels above the upper limit (116.591 pg/ml), including 10 patients with epilepsy (7/15, 46.7%), 5 patients with myasthenia gravis (5/6, 83.3%), 3 patients with DMD (3/7, 42.9%), and 1 patient with viral encephalitis (1/2, 50%)." (PMID 35498801, 2022). "In addition, dystrophin is a component of gamma-aminobutyric acid (GABA)ergic synapses and plays a role in normal cognitive (i.e., episodic memory) processes; the absence of dystrophin is associated with epilepsy." (PMID 36531133, 2022). "Since epilepsy is also supposed to constitute a comorbidity of DMD, it is hypothesized that dystrophin plays a role in neuronal excitability." (PMID 27458343, 2016). "In line with our results, hippocampal dystrophin levels were not altered in other pre-clinical epilepsy models such as the pentylenetetrazole and status epilepticus model." (PMID 27458343, 2016). "Dystrophin is ubiquitously expressed in the hippocampus and cerebellum of AK rats and in human hippocampal tissue from epilepsy patients with and without HS as proven by Western blot and immunofluorescent analysis in this study." (PMID 27458343, 2016). "Based on a general visual examination in all performed stainings, the amount of dystrophin positive astrocytes seems to be higher in the epilepsy patient (here: non-sclerotic) compared to the post-mortem control." (PMID 27458343, 2016).
rhabdomyosarcoma (11 papers, 2012 to 2025). A rare aggressive malignant mesenchymal neoplasm arising from skeletal muscle. "In mice, the loss of either of two DGC proteins, dystrophin or α-sarcoglycan, is associated with a high incidence of rhabdomyosarcoma (RMS)." (PMID 31054580, 2019). "Next, we sought to confirm whether these SSOs could restore dystrophin protein by inducing DMD exon 50 skipping in DMD model cells, human rhabdomyosarcoma cells with a DMD intron 50–57 deletion mutation induced by the CRISPR/Cas9 system." (PMID 33805378, 2021). "An analysis of knockout mouse models for two of the DGC components, dystrophin (mdx) and α-sarcoglycan, demonstrated that primary defects in the DGC are sometimes associated with the formation of rhabdomyosarcomas (RMS)." (PMID 31054580, 2019). "Intragenic deletions of the dystrophin-encoding and muscular dystrophy-associated DMD gene have been recently described in gastrointestinal stromal tumor (GIST), rhabdomyosarcoma (RMS) and leiomyosarcoma (LMS)." (PMID 25143820, 2014). "Additionally, we demonstrate that the 3-mix LNA-based SSO cocktails promote the skipping of exon 51 in DMD at the endogenous DMD locus in the human rhabdomyosarcoma cell line." (PMID 29768479, 2018). "Furthermore, the LNA-based SSO cocktails display high exon 51 skipping activities on endogenous DMD mRNA in human rhabdomyosarcoma cells." (PMID 29768479, 2018). "Intragenic deletions of the dystrophin-encoding and muscular dystrophy-associated DMD gene have been recently described in many common human mesenchymal tumors, including gastrointestinal stromal tumor (GIST), rhabdomyosarcoma (RMS) and leiomyosarcoma (LMS) which show myogenic differentiation." (PMID 25143820, 2014). "In contrast, the SH-SY5Y neuroblastoma cell line and, in particular, the two rhabdomyosarcoma cell lines (RD and SJCRH30) were chosen for their good expression of the muscle and brain dystrophin isoforms (right)." (PMID 23028937, 2012). "In fact, it was connected to a lack of dystrophin expression in rhabdomyosarcoma cells." (PMID 40114059, 2025).
autism spectrum disorder (10 papers, 2017 to 2025). A spectrum of developmental disorders that includes autism, and Asperger syndrome. "The expression of dystrophin isoforms was significantly associated with genes implicated in neurodevelopmental disorders, like autism spectrum disorders or attention-deficit hyper-activity disorders, which are known to be associated to DMD." (PMID 28974727, 2017). "Then we present a brief overview of the literature about similar cases and about the potential role of the dystrophin protein in the neurobiology of autism spectrum disorder." (PMID 34640386, 2021). "Then, we conduct a brief overview of the updated literature data about the potential role of the dystrophin protein in the neurobiology of autism spectrum disorder." (PMID 34640386, 2021). "The lack of dystrophin in the brain has a negative effect on cognitive functions and has been associated with developmental disorders, including autism spectrum disorder." (PMID 32877421, 2020). "The authors aimed to evaluate how the symptoms of Attention-Deficit/Hyperactivity Disorder (ADHD), Obsessive-Compulsive Disorder (OCD), or Autism Spectrum Disorder (ASD), and genotype are related to DMD genotype." (PMID 40451248, 2025).
cardiac hypertrophy (10 papers, 2015 to 2022). "The rescued dystrophin can prevent and attenuate cardiac hypertrophy in a DMD mouse model induced by a truncation mutation of dystrophin." (PMID 36428995, 2022). "As the hallmark of cardiac hypertrophy we also measured cardiomyocyte size from dystrophin-stained EHT cross sections and found hypertrophied cells in AE-EHTs (76 μm2 on average) compared to control EHTs (58 μm2 on average)." (PMID 31391475, 2019). "At 90 dps, 70% of the animals presented cardiac hypertrophy and fibrosis (HH group) associated with preserved dystrophin expression and cardiac function." (PMID 29267303, 2017). "The remaining 30% presented cardiac hypertrophy+dilated hearts (HD group), decreased dystrophin and increased calpain-1 expression associated with systolic and diastolic dysfunction." (PMID 29267303, 2017). "ERK1/2 activation protects myofibers from damage and contributes to cardiac hypertrophy and protein expression of dystrophin and utrophin in skeletal muscle." (PMID 35065666, 2022). "This study was undertaken to evaluate dystrophin and calpain-1 in the transition from compensated cardiac hypertrophy to HF." (PMID 29267303, 2017). "Using a forced exercise model we show that repeat treatment with Pip6f-PMO induced high levels of dystrophin restoration in heart which prevented cardiac hypertrophy and stabilised other cardiac parameters as determined by cine-MRI." (PMID 25758104, 2015). "In addition, the transition of compensated cardiac hypertrophy to heart failure is accompanied by expression decrease in the dystrophin." (PMID 36428995, 2022). "The heart weight to tibia length ratio was similar in dystrophin-deficient mdx mice (5.5 ± 0.2 vs. 5.9 ± 0.2 mg/mm, respectively) at 22 weeks old and age-matched control C57BL10 mice, indicating no cardiac hypertrophy in mdx mice at this age." (PMID 30348945, 2018).
cystic fibrosis (10 papers, 2006 to 2024). Autosomal recessive disorder caused by pathogenic variants in the CFTR gene (cystic fibrosis transmembrane conductance regulator), which encodes a chloride and bicarbonate channel expressed in epithelial cells, and follow the diagnosis criteria. "Thus, cDNA for the human CFTR gene, the therapeutic gene for cystic fibrosis, has one hotspot consensus sequence and cDNA for the human dystrophin gene, the therapeutic gene for DMD, has three such potential hotspots." (PMID 16529656, 2006). "In the human genome, exceptionally long introns are found in genes with a wide variety of cellular and developmental functions, including genes with important roles in some diseases, e.g., dystrophin in DMD and cystic fibrosis transmembrane conductance regulator (CFTR) in cystic fibrosis." (PMID 34907472, 2022). "For example, the duplication of exons 3–7 in DMD was incidentally identified by array comparative genomic hybridization in a girl without a family history of DMD, who was affected by cystic fibrosis and maturity-onset diabetes of the young type 5 (MODY5) due to a classical 17q12 microdeletion." (PMID 35615378, 2022).
developmental delay (10 papers, 2008 to 2025). "The heterogeneity of Xp21 genetic mutations causing the disorder results in a spectrum of decreased dystrophin expression and cognitive delays." (PMID 38525359, 2024). "It is difficult to conclude whether the developmental delays noted in some of our patients could be attributed to the underlying DMD deletion or whether they could have a separate cause." (PMID 36424846, 2023). "Case 6 showed a translocation between chromosomes 5 and X, which impacted the DMD gene intron 1 and manifested as developmental delay, muscle weakness, high CK levels, and pronounced DMD symptoms since childhood." (PMID 39575648, 2025). "This patient, #1497, presented mild muscle weakness, microophthalmia,vitreous hyperplasia, severe cognitive delay and, interestingly, almost normal dystrophin expression in skeletal muscle." (PMID 26284620, 2015). "Our findings revealed that individuals with DMD deletions exhibited a higher incidence of certain phenotypes, including calf hypertrophy and developmental delay, including speech delay, than those with non-DMD mutations." (PMID 38057384, 2023).
melanoma (10 papers, 2011 to 2024). A malignant, usually aggressive tumor composed of atypical, neoplastic melanocytes. "A previous study showed DMD gene deletions in melanoma cell lines; the occurrence of DMD mutations correlated with increased migration, whereas re-expression of DMD attenuated the phenotype." (PMID 23169061, 2013). "In support of this view, dystrophin has been linked to human cancer, as its frequent inactivation was shown to be involved in the pathogenesis of malignant melanoma." (PMID 21533183, 2011). "Specifically in the case of melanoma, DMD was down-regulated as compared to benign nevi that already showed a reduced expression compared to normal skin." (PMID 29596374, 2018). "In melanoma cell lines, the DMD gene was found with deletions while the protein was frequently absent or down-regulated." (PMID 29596374, 2018). "We also observed that DMD expression was diminished in melanoma compared to benign nevi that already showed a reduced expression compared to normal skin samples." (PMID 27391342, 2017). "DMD was found frequently under-expressed in melanoma cell lines, and this reduced expression was due to gene deletions." (PMID 27391342, 2017). "Furthermore, DMD has been found to be downregulated in several tumors affecting the nervous system, hematological malignancies, melanoma and carcinomas, including lung adenocarcinoma, prostate, colon and breast cancer." (PMID 35197484, 2022). "Digital karyotyping and multiplex PCR analysis of cell lines derived from established metastatic melanomas revealed DMD deletions in the M1 (in-frame deletion of exons 3–29), RPMI-7951 (in-frame deletion of exons 17–30) and WM-793 (out-of-frame deletion of exons 42–43) cell lines." (PMID 33188621, 2021). "In comparison to normal melanocytes, 32/37 melanoma cell lines exhibited a reduced DMD expression." (PMID 33188621, 2021). "We also found lower DMD expression in melanoma compared to normal skin." (PMID 27391342, 2017). "Notably, in melanoma cell lines dystrophin knock-down enhanced migration and invasion, whereas re-expression attenuated migration and induced a senescent phenotype, fully in line with a tumor suppressor role of dystrophin." (PMID 21533183, 2011). "These variants are considered to be melanoma-specific since no new variants were found in cell lines expressing Dp427m that may affect dystrophin function." (PMID 33188621, 2021). "In addition, in vitro down-regulation of DMD enhanced melanoma cells migration and invasion." (PMID 27391342, 2017).
myonecrosis (10 papers, 2008 to 2025). "Altogether, these data demonstrated that dystrophin deficiency in both R-DMDdel52 and R-DMDdup10-17 Sprague Dawley rats induces similar myonecrosis-driven cardiac remodelling and a highly specific notched T wave leading to an increase of the QTpc biomarker." (PMID 40490752, 2025). "Together, these biomarkers reveal ongoing, dystrophin-deficiency-driven myonecrosis in both skeletal and cardiac muscle." (PMID 40490752, 2025). "A large variety of factors are associated with myonecrosis, including abnormal calcium handling, reactive oxygen species (ROS) and inflammatory molecules in dystrophin-deficient muscles." (PMID 36613804, 2022). "In dystrophin-deficient Golden retriever muscular dystrophy (GRMD) dogs, evidence of RIPK3-driven myonecrosis is also found in the diaphragm and the heart." (PMID 36613804, 2022). "By removing the mechanical protection conferred by the membrane complex normally organised around dystrophin, the duplication resulted in myonecrosis induced by membrane damage in the skeletal and heart muscles, as evidenced by the high blood levels of the two released biomarkers, MYOM3 and hs-cTnT." (PMID 40490752, 2025). "We also show that lack of dystrophin is associated with a number of previously unsuspected abnormalities of muscle fibre structure and function that do not appear to be directly associated with myonecrosis." (PMID 25987977, 2015). "An upregulation of Tropomyosin as a compensation mechanism in the contractile apparatus while Dystrophin is lacking can be seen in the early stages of the diseases until fibrosis, myonecrosis, and replacement with fatty tissue take place." (PMID 41227334, 2025). "We strongly focus on myonecrosis and the associated inflammation and oxidative stress in DMD muscle, as the lack of dystrophin causes repeated bouts of myonecrosis, which are the key events that initiate the resultant severe dystropathology." (PMID 32224496, 2020). "A key aim for DMD therapies is to prevent myonecrosis and to directly stabilise the myofibres, ideally by replacing the non-functional dystrophin using various gene delivery or molecular strategies, with recent promising progress." (PMID 32224496, 2020). "Therefore, the present results support previous observations (with Western blotting, ELISA and immunocytochemistry techniques) that constitutional properties of the EOM compensate for the lack of dystrophin, allowing a better response against myonecrosis." (PMID 23823696, 2013).
breast carcinoma (9 papers, 2011 to 2025). "In one study, conditioned media from human breast cancer cell lines accelerated the differentiation of human muscle stem cells but reduced the expression of dystrophin and MYH in differentiated muscle cells associated with decreased AKT activity." (PMID 38973385, 2024). "This is reflective of breast cancer associations reported in the literature [KMT2C:, DMD:, TTN:, RYR2:]." (PMID 40685627, 2025). "The clinical correlation pathological study of RACGAP1, IRF7, and DMD showed that RACGAP1 was highly expressed in the high-risk group, indicating that RACGAP1 has a greater impact on patients with breast cancer infected with SARS-CoV-2." (PMID 36060002, 2022). "Interestingly, in sporadic breast cancer, the median frequency of DMD alterations (3.95%) was higher than those of BRCA1 (1.95%) and BRCA2 (3.4%)." (PMID 33188621, 2021). "Moreover, the median frequency of DMD alterations in sporadic breast cancer was higher than the median frequency for BRCA genes in the same tumors (3.95% vs 1.95% and 3.40% for DMD, BRCA1 and BRCA2, respectively)." (PMID 27391342, 2017). "Moreover, utrophin, the highly related autosomal paralogue of dystrophin, represents a tumor suppressor candidate, owing to its frequent disruption in human malignant tumors and its capability to inhibit breast cancer cell growth." (PMID 21533183, 2011).
Obesity (9 papers, 2013 to 2024). Accumulation of substantial excess body fat. "Specifically, the EGFL6 gene is associated with obesity-related inflammation in children, and the DMD gene with muscle inflammation." (PMID 39844836, 2024). "Furthermore, while such metabolic changes are minor in female mdx carrier mice, they do suggest that female humans harboring dystrophin mutations could be susceptible to metabolic dysfunction particularly in the context of diet-induced obesity or aging." (PMID 32636760, 2020). "Obesity was present in 3% (5/143) of the DMD or BMD patients and in 16% (35/219) of the carriers (overall 40/362, 11%)." (PMID 23870371, 2013). "Nevertheless, epidemiological evidence linking female dystrophin mutation carriers with increased prevalence of obesity, type 2 diabetes, or metabolic dysfunction is lacking." (PMID 32636760, 2020). "Obesity often co-occurs with GSD II, MWS, HCP, chromosomal aberration 46XX, del (q24.21q24.23) (N% = 100%, ASR = 2.8) and z DMD (N% = 42.9%, ASR = 2.7), but rarely with CP (N% = 8.8%, ASR = −2.4)." (PMID 34073813, 2021). "Age, ambulatory status, completing a 10 m walk/run in 7 s and dystrophin isoforms maintained did not predict obesity." (PMID 36014811, 2022).
Respiratory insufficiency (9 papers, 2017 to 2025). "The loss of respiratory muscle in DMD culminates in respiratory insufficiency and eventually premature death." (PMID 37269541, 2023). "Available DMD animal models were sufficient to demonstrate micro-dystrophin efficacy on earlier onset skeletal muscle pathology underlying loss of ambulation and respiratory insufficiency in patients." (PMID 33651713, 2021). "Since the mdx/utrn-/- mice lack the expression of both dystrophin and utrophin, this results in early onset diaphragm weakness and disease progression with respiratory insufficiency and hypoventilation that closely mimics human disease." (PMID 39919154, 2025). "Symptomatic therapy has prolonged survival by limiting deaths resulting from respiratory insufficiency, but there is currently no effective therapy for most patients with DMD." (PMID 31444390, 2019).
Insulin resistance (8 papers, 2015 to 2025). Increased resistance towards insulin, that is, diminished effectiveness of insulin in reducing blood glucose levels. "It has been established that low levels of dystrophin are associated with insulin resistance, T2D, and impaired vasodilation in humans." (PMID 41149633, 2025). "Recently it was shown that the dystrophin–glycoprotein complex interacts with the insulin receptor and regulates insulin signalling in skeletal muscle, suggesting that mutations in this complex contribute to the development of insulin resistance and T2D." (PMID 35796564, 2022). "Further ECM components potentially representing targets for insulin resistance are hyaluronan, the dystrophin-dystroglycan complex as well as MMP9." (PMID 32265741, 2020). "Impaired cytoskeletal anchoring of DMD may lead to insulin resistance." (PMID 34454586, 2021).